HDAC11 (histone deacetylase 11)
Diseases named in the same sentence as HDAC11 in open-access papers (continued):
Sharing a sentence is not in itself a finding about the gene and the disease.
depression (1 paper, 2025). "This study not only provides experimental evidence for targeting HDAC11 to promote synaptic regeneration and repair neural networks but also establishes the potential of HDAC11 as a novel therapeutic target for depression." (PMID 41471347, 2025).
diabetic retinopathy (1 paper, 2017). "Decreased IL-10 levels are seen in diabetic retinopathy patients that have been suggested to be due to increased HDAC11 activity in conjunction with miR-19a in peripheral B cells of diabetic retinopathy patients." (PMID 29085333, 2017).
experimental autoimmune encephalomyelitis (1 paper, 2018). An autoimmune demyelinating disease of the central nervous system that is produced experimentally in animals by the injection of homogenized brain or spinal cord in Freund's adjuvant. "Our results indicate that the loss of HDAC11 in KO mice significantly reduces clinical severity and demyelination of the spinal cord in the post-acute phase of experimental autoimmune encephalomyelitis." (PMID 30456376, 2018). "Here, we investigate the functional role of HDAC11 in experimental autoimmune encephalomyelitis, a mouse model for MS." (PMID 30456376, 2018).
Glucose intolerance (1 paper, 2023). Glucose intolerance (GI) can be defined as dysglycemia that comprises both prediabetes and diabetes. "Adipocyte-specific knockout of HDAC11 in mice attenuates HFD-induced weight gain and glucose intolerance." (PMID 37607030, 2023).
hearing loss (1 paper, 2025). "In animal experiments, we further verified the ameliorative effect of HDAC11 overexpression on hearing loss in aged mice." (PMID 40667486, 2025).
Huntington disease (1 paper, 2022). Huntington disease (HD) is a rare neurodegenerative disorder of the central nervous system characterized by unwanted choreatic movements, behavioral and psychiatric disturbances and dementia. "We suggest that more research is needed to elucidate the exact mechanism of HDAC11-mediated Huntington's disease." (PMID 35651655, 2022).
Hyperinsulinemia (1 paper, 2021). An increased concentration of insulin in the blood. "To date, substantial evidence is absent regarding the regulatory effect of class IV, HDAC11, on insulin secretion; however, deletion of HDAC11 has been mentioned to suppress high fat-induced hyperinsulinemia in mice." (PMID 34071497, 2021).
liver diseases (1 paper, 2025). "Given B6’s favorable pharmacokinetic profile and its preferential accumulation in the liver, we propose that B6 will serve as an invaluable tool for future research on HDAC11 in the context of liver diseases." (PMID 39976110, 2025).
lung fibrosis (1 paper, 2024). "In contrast to Class I and Class II HDACs, our knowledge regarding the role and function of Class IV HDAC (HDAC11) in lung fibrosis is limited." (PMID 39193364, 2024).
lymph node tumor (1 paper, 2021). "For example, pharmacological inhibition of HDAC11 decreases lymph node tumor growth, but also enhances metastasis from the lymph node to distant sites." (PMID 34595180, 2021). "However, caution is required when using HDACis because in addition to a suppression of lymph node tumor growth, pharmacological inhibition of HDAC11 enhances metastasis from the lymph node to distant sites." (PMID 34595180, 2021).
melanoma (1 paper, 2022). A malignant, usually aggressive tumor composed of atypical, neoplastic melanocytes. "The results indicate that, as in the human melanomas, Mitf correlated well with expression of Ctnnb1, HDAC11 and Psen2, but unlike the human tumors Myc was not correlated with Mitf." (PMID 35771179, 2022).
myeloma (1 paper, 2021). "In summary, we have demonstrated that HDAC11 is central to orchestrating the transformation of an activated B cell into a plasma cell and that HDAC11 regulates the transcriptional activity of multiple genes essential to plasma cell and myeloma cell proliferation and survival." (PMID 34793338, 2021). "Collectively, our findings suggest that HDAC11 interacts with the IRF4/BLIMP1/MYC transcriptional network, which is critically dysregulated in myeloma genesis, and HDAC11 inhibition offers a potential therapeutic strategy for MM treatment." (PMID 34793338, 2021). "HDAC11 inhibition, likely via its inactivation of IRF4, delivers a cytotoxic insult to myeloma cells in vitro." (PMID 34793338, 2021). "In contrast, we have demonstrated that the selective inhibition of HDAC11 promoted the deacetylation of IRF4 — a vital signal pathway essential to the biology and oncogenic mechanism of plasma cell myeloma — and may provide a more effective translational strategy." (PMID 34793338, 2021). "Moreover, HDAC11 accomplishes this through direct interaction with the IRF4 transcription factor, which has a well-established role in controlling B cell and plasma cell differentiation as well as myeloma genesis." (PMID 34793338, 2021).
myopia (1 paper, 2020). "Some identified variants showed precise scaling in corneal curvature and eye elongation (i.e. axial length) to maintain eyes in emmetropia (i.e. HDAC11/FBLN2 rs2630445, RBP3 rs11204213); others exhibited association with myopia with little pleiotropic effects on eye elongation." (PMID 32193507, 2020).
plasma cell disorders (1 paper, 2021). "Collectively, HDAC11 expression was increased in plasma cell dyscrasias as compared with plasma cells isolated from healthy donor marrow samples, but expression was largely consistent throughout plasma cell disorders even in the face of therapy resistance." (PMID 34793338, 2021).
prostate tumor (1 paper, 2024). "Flow cytometry data indicated that HDAC11 downregulation notably enhanced the infiltration of CAR-T cells within the tumor microenvironment of prostate tumor mice xenografts." (PMID 38835760, 2024).
pulpitis (1 paper, 2025). Inflammation of the dental pulp. "HDAC11 (P < .05) downregulated in the pulpitis group compared to the healthy group, but other enzymes did not change, which indicated histone acetylation may be partly mobilized." (PMID 40580029, 2025).
retinal degeneration (1 paper, 2017). Degeneration of the retina. "Our transcriptomic data also revealed an increase in a number of non-apoptotic pathway genes that have been implicated in retinal degeneration, such as a number of poly-ADP-ribose-polymerases (PARP9, PARP14, PARP15) and histone deacetylases (HDAC7, HDAC10, HDAC11)." (PMID 29263354, 2017).
schizophrenia (1 paper, 2017). A major psychotic disorder characterized by abnormalities in the perception or expression of reality. "The emerging association between HDAC11 and schizophrenia is interesting as it should be considered during the development of therapeutic drugs." (PMID 28928414, 2017). "In their review they note that Hdac11 is expressed in the hippocampus and such patterns provide a spatial association with schizophrenia but emphasise that functional inferences cannot be drawn from this." (PMID 28928414, 2017). "The results of this study demonstrate that Hdac11 knockout mice provide a means to examine the functional association between HDAC11 and schizophrenia-associated FEZ1." (PMID 28928414, 2017). "Furthermore, it would be interesting to investigate the response of Hdac11 knockout mice to phencyclidine, which is reported to result in a variety of phenotypes associated with schizophrenia including hyperlocomotion." (PMID 28928414, 2017). "However, in differentiating neural cells we observed decreased expression of schizophrenia-associated gene Fez1 (fasciculation and elongation protein zeta 1), a gene previously reported to be regulated by HDAC11 activity." (PMID 28928414, 2017). "Given previous associations between HDAC11, FEZ1 and schizophrenia, a goal of future research should be to examine the performance of homozygous Hdac11 knockout mice in behavioural tests." (PMID 28928414, 2017). "This suggests that HDAC11 has an age-dependent, brain region specific function in regulating FEZ1, a gene associated with schizophrenia." (PMID 28928414, 2017). "The report of reduced FEZ1 gene expression in the hippocampus of patients with schizophrenia is particularly relevant as this was seen in the homozygous Hdac11 knockout mice." (PMID 28928414, 2017).
Sepsis (1 paper, 2023). Sepsis is defined as life-threatening organ dysfunction caused by a dysregulated host response to infection. "Histone deacetylase 11 (HDAC11) plays an important role in sepsis." (PMID 38022612, 2023).
skin aging (1 paper, 2021). The gradual irreversible changes in structure of skin that occur as a result of the passage of time.. "Collectively, HDAC4 and HDAC11 were decreased in both UV-irradiated and intrinsically aged skin, suggesting that they may play a universal role in increased histone acetylation associated with skin aging." (PMID 33670779, 2021). "Further research is warranted to assess the role of HDAC4 and HDAC11 in skin aging." (PMID 33670779, 2021).
spinal muscular atrophy (1 paper, 2013). A motor neuron disease that affect the muscles, and characterized by muscle weakness and atrophy resulting from progressive degeneration and irreversible loss of the anterior horn cells in the spinal cord (i.e., lower motor neurons) and the brain stem nuclei. "Independent analysis of the HDAC11 protein network revealed association with the SMN protein subnetwork that affects RNA splicing of minor introns, suggesting that, when misregulated, the HDAC11 network can contribute to the phenotype of spinal muscular atrophy patients." (PMID 23752267, 2013).
tumor (61 papers, 2012 to 2026). "Histone deacetylase 11 (HDAC11) is the sole member of class IV HDACs, implicated in tumor growth, immune regulation, and oxidative stress injury." (PMID 40386380, 2025). "In the LinkedOmics database, CBX2, NOTCH3, HDAC6 and HDAC11 were linked with tumor purity and TNM stage." (PMID 38702698, 2024). "In line with this prediction, adoptive transfer of HDAC11-deficient T cells into a syngeneic lymphoma tumor model generated a better anti-tumor response than WT T cells." (PMID 34512154, 2021). "The 9-gene group includes KIF14, a known oncogene associated with aggressive tumor qualities in many cancers, linking HDAC11 epigenetic regulation to the hallmarks of aggressive cancers." (PMID 28252645, 2017). "In a murine Hdac11 knockout model, it was shown that tumor growth was more rapid in Hdac11-deficient mice compared with the wild-type mice." (PMID 25915736, 2015). "In addition to its role in metastasis, HDAC11 is implicated in maintaining stemness and promoting tumor development in HCC." (PMID 39620228, 2024). "In contrast, HDAC11 had a significantly lower expression in high-risk M3 tumours (p < 0.001)." (PMID 33316946, 2020). "HDAC11 expression was significantly lower in high-risk tumours." (PMID 33316946, 2020). "For example, in KIRC patients with low expression of Purinergic genes, the use of HDAC inhibitors targeting HDAC8, HDAC10, and HDAC11 may help to inhibit the invasive and metastatic ability of tumor cells, which is closely associated with a good prognosis for patients." (PMID 38180750, 2024). "In addition, we found that the high expression of HDAC11 may cause tumor cell immune desertion and inhibit cell infiltration in the TME." (PMID 37649598, 2023). "The overexpression of HDAC11 has been observed in several malignancies, where it promotes tumor progression by repressing tumor suppressor genes and modulating immune evasion mechanisms." (PMID 40649728, 2025). "Tumor exosomes containing miR-145 have been shown to downregulate HDAC11 in TAMs, unleashing IL-10 production and thereby promoting tumor immune evasion." (PMID 40358164, 2025). "Other EpiGs highly induced in tumor tissues, such as HDAC11 and CBX2, are attracting significant attention as chromatin regulators capable of predicting prognosis and therapeutic responses." (PMID 40504449, 2025). "For example, HDAC11 has a positive correlation with tumor growth, but its incongruously high expression also conferred longer DFS and OS in pancreatic tumor patients." (PMID 38536720, 2024). "Elevated HDAC11 expression is able to boost tumor survival and proliferation within the lymph nodes, but declined HDAC11 promotes a migratory phenotype, which leads to significantly increased migration from the lymph node to distant organs." (PMID 38374872, 2024). "The exact role of HDAC11 in tumor progression is currently still under debate; however, it seems that there are significant differences depending on the tumor type." (PMID 39409979, 2024). "FT895, an HDAC11 inhibitor, exhibits potent anti-tumor effects on MPNST cells and enhances the cytotoxicity of cordycepin against MPNST." (PMID 38203448, 2023). "This was demonstrated as tumor-bearing HDAC11-knockout mice presented an increased number of MDSCs compared to wild-type (WT) tumor-bearing control mice." (PMID 35267487, 2022). "In summary, our study shows that HDAC11 inhibits tumor metastasis in CRC through suppressing MMP3 expression." (PMID 35399729, 2022). "Acetylation lysine residue 335 of ENO1 by histone deacetylase 11 (HDAC11) causes loss of ENO1 activity and suppress the glycolysis in tumor cells." (PMID 34671213, 2021). "HDAC1 (p = 0.05), HDAC3 (p = 0.02), the second probe of HDAC5 (p = 0.04) and of HDAC7 (p = 0.03), and HDAC8 (p = 0.004), were increased in tumours with 8q gain, while HDAC11 was decreased (p = 0.002)." (PMID 33316946, 2020).
tumor (continued). "Tumor-carrying HDAC11 knockout mice (HDAC11-KO) showed more MDSC inhibition, and the transition from immature myeloid cells to MDSCs required a reduction in HDAC11 expression." (PMID 33027968, 2020). "Unexpectedly, the inhibition of HDAC11 led to significantly increased LuM, especially when normalizing to the reduced AxLN tumor sizes." (PMID 31519896, 2019). "Here, the authors report that while histone deacetylase 11 (HDAC11) inhibition suppresses tumor growth within the LN, it also promotes cancer cell migration out of the LN to form distant metastasis, and therefore suggest caution with HDAC inhibitors." (PMID 31519896, 2019). "Genetic and pharmacologic blockade of HDAC11 decreases LN tumor growth, yet substantially increases migration and distant metastasis formation." (PMID 31519896, 2019). "Our study identified a group of cell cycle-promoting genes regulated by HDAC11, being both predictors of unfavorable patient outcome and essential for tumor cell viability." (PMID 28252645, 2017). "In contrast with other HDACi, inhibition of HDAC11 in this study lowered IL-10-producing Treg numbers which favoured the elimination of these tumour cells." (PMID 22461998, 2012). "Enhanced tumour cell cytotoxicity also occurs following RNAi-mediated HDAC11 inhibition, increasing OX40L expression in Hodgkin lymphoma cell lines associated with elevated TNF-α and IL-17 levels in the supernatant." (PMID 22461998, 2012). "A high correlation between HDAC11 and tumor development, microvascular invasion, tumor differentiation, and clinical staging in patients with LIHC suggests that it may have a regulatory role in maintaining cancer stemness." (PMID 39512688, 2024). "Similarly, class III HDACs (sirtuins) and the only member of class IV (HDAC11) are differentially expressed in malignant tissues with prevalent upregulation across TCGA tumor types." (PMID 39063083, 2024). "(D) The mRNA expression of HDAC11 in L-DOXR cells-derived tumor tissue was measured by RT-qPCR." (PMID 38536720, 2024). "In these cancers, HDAC11 promotes tumor cell migration, stemness, and drug resistance." (PMID 39620228, 2024). "Interestingly, HDAC1, HDAC2, HDAC4, and HDAC11 showed a significant upregulation in tumor compared to normal liver tissue." (PMID 39529166, 2024). "Compared with normal tissues, the expression of CNV-amplified HA regulators was significantly increased in tumor tissues (e.g. HDAC3 in KIRC), while the expression of CNV-deficient HA regulators was significantly decreased (e.g. KAT2B, HDAC11 and PBRM1 in KIRC)." (PMID 37553641, 2023). "Furthermore, we identified upregulated DEGs in TN tumours including drug targets histone deacetylase enzymes (e.g. HDAC1, HDAC2, and HDAC11) implicated in the epigenetic regulation of gene expression." (PMID 36220861, 2022). "We previously published that monosomy 3 is associated with tumor inflammation: here, we observe a negative correlation between HDAC11 expression and inflammatory TIL and TAM markers." (PMID 34439300, 2021). "HDAC11-deficient T cells not only accelerate GVHD, but also may provide a better anti-tumor response when considering their elevated inflammatory capabilities." (PMID 34512154, 2021). "Moreover, the expression of HDAC5 and HDAC11 are positively parallel with tumor stage and grade, T, N, and M stage." (PMID 34308568, 2021). "With the success of therapeutics targeting both the tumor and cellular immune effectors, it will be important to define the immunological impact of HDAC11 inhibitors because this may complement the observed anti-MM activity." (PMID 34793338, 2021). "Interestingly, while genetic and pharmacologic blockade of HDAC11 decreases LN tumor growth, it substantially increases migration and promotes distant metastasis formation." (PMID 31519896, 2019).